CD99L2 (CD99 molecule like 2)
Description:
Plays a role in a late step of leukocyte extravasation helping cells to overcome the endothelial basement membrane. Acts at the same site as, but independently of, PECAM1 (By similarity). Homophilic adhesion molecule, but these interactions may not be required for cell aggregation (By similarity).
Synonyms: MIC2L1; CD99B
Tractability: Antibody: UniProt places it where antibodies can reach, with high confidence; UniProt predicts a signal peptide or a membrane-spanning region; its Gene Ontology location is reachable by antibodies, with medium confidence; the Human Protein Atlas places it where antibodies can reach. PROTAC: ubiquitination databases record sites on it; its protein half-life has been measured.
Gene: Protein-coding gene on chromosome X (150,766,336 to 150,898,816, reverse strand). Ensembl gene ENSG00000102181.
Subcellular location: Cell membrane; Cell junction; Secreted
Subcellular location (Human Protein Atlas): Plasma membrane; Predicted to be secreted
Pathways (Reactome):
Hemostasis: Cell surface interactions at the vascular wall
Gene Ontology:
Molecular function: protein binding
Cellular component: extracellular region; focal adhesion; adherens junction; anchoring junction; cell surface; plasma membrane
Homologues: Orthologues: chimpanzee CD99L2 (99% identical), macaque CD99L2 (95% identical), rabbit CD99L2 (81% identical), dog CD99L2 (68% identical), pig CD99L2 (67% identical), mouse Cd99l2 (65% identical), rat Cd99l2 (63% identical), guinea pig CD99L2 (53% identical), tropical clawed frog cox20 (49% identical), zebrafish cd99l2 (37% identical). Paralogues in human: CD99 (23% identical).
Diseases named in the same sentence as CD99L2 in open-access papers:
CD99L2 is named in the same sentence as 13 diseases in open-access papers, as found by Europe PMC text mining. Sharing a sentence is not in itself a finding about the gene and the disease. The quoted sentences say what the papers report.
Ewing sarcoma (2 papers, 2020 to 2025). A small round cell tumor that lacks morphologic, immunohistochemical, and electron microscopic evidence of neuroectodermal differentiation. "We then used ligand-binding assays to test the role of CD99 and CD99L2 as the GDF6 prodomain receptor in Ewing sarcoma." (PMID 33147457, 2020). "GDF6 pro-FLAG bound to control siRNA-transfected A673 cells, and this binding was significantly reduced by silencing of CD99 and/or CD99L2, indicating that the GDF6 prodomain binds CD99/CD99L2 in Ewing sarcoma." (PMID 33147457, 2020). "Growth and differentiation factor 6 (GDF6) in Ewing sarcoma, paired immunoglobulin-like type 2 receptors (PILRs), CD99 antigen-like protein 2 (CD99L2), and CD99 itself were shown to act as ligands of CD99 and contribute to the regulation of the immune system." (PMID 41514929, 2025).
ovarian carcinoma (2 papers, 2015 to 2021). A malignant neoplasm originating from the surface ovarian epithelium. "In mesenchymal-like ovarian cancer cells, silencing of CD99L2 causes colony compaction, indicating that the protein plays a negative role in cell-to-cell adhesion." (PMID 34771489, 2021). "CD99L2 is encoded by one of the six mesenchymal genes, which are part of an EMT signature in ovarian carcinoma." (PMID 34771489, 2021). "Here, we designed small-scale siRNA screens targeting these six mesenchymal signature genes (CD99L2, EMP3, ITGA5, SYDE1, VIM, ZEB1) to explore their functional relevance and their roles during EMT reversal by nintedanib (BIBF1120) in a mesenchymal-like SKOV3 ovarian cancer cell line." (PMID 26061747, 2015).
breast carcinoma (1 paper, 2021). "AGR2, APOE, AQP3, and CD99L2 may be of particular interest for the epithelial differentiating action exerted by circDOCK1-1 in TNBC-mes breast cancer cells." (PMID 34771489, 2021).
lung carcinoma (1 paper, 2022). "The CD99L2 gene has been reported to be prognostic for urothelial cancer (unfavorable), pancreatic cancer (favorable), and lung cancer (favorable)." (PMID 35039759, 2022).
melanoma (1 paper, 2020). A malignant, usually aggressive tumor composed of atypical, neoplastic melanocytes. "Compared to the amount of molecules that are known to be involved in leukocyte diapedesis, the knowledge on their role in melanoma diapedesis is limited, although many of these molecules are expressed in melanoma cells such as CD99, CD99L2 and CD54." (PMID 33172202, 2020).
mental retardation (1 paper, 2006). "For CD99L2, a possible association with diseases involving mental retardation could be implicated also by its putative function: Its high expression in neuronal cells is conserved in mammals and zebra fish and suggests a dominant role in neural development." (PMID 16503986, 2006).
spastic ataxia (1 paper, 2026). "Unsolved cases are included in the Solve-RD cohort and subjected to gene-burden analysis, providing evidence for loss-of-function variants in X-chromosomal CD99L2 causing spastic ataxia." (PMID 41690933, 2026).
cancer (1 paper, 2024). A tumor composed of atypical neoplastic, often pleomorphic cells that invade other tissues. "CD99 antigen and CD99 antigen-like protein 2 (CD99L2) are related transmembrane proteins that form heterodimers and play important roles in leukocyte extravasation and cancer." (PMID 39684750, 2024).
infection (1 paper, 2023). The state of being infected such as from the introduction of a foreign agent such as serum, vaccine, antigenic substance or organism. "To further explore whether this phenomenon exists in other leukocytes, we used Jurkat cells and found that CD99 and CD99L2 were significantly downregulated after ATCC 33277 infection, as shown by both Western blotting and flow cytometry." (PMID 37199607, 2023).
CD99L2 also shares sentences with these, for which no sentence is quoted: autism spectrum disorder (1 paper); colorectal cancer (1); pancreatic cancer (1); tumor (1).